RBP4 (retinol binding protein 4)
Diseases named in the same sentence as RBP4 in open-access papers (continued):
Sharing a sentence is not in itself a finding about the gene and the disease.
type 2 diabetes (140 papers, 2008 to 2026). "uDPP4 activity was positively associated with albuminuria, urinary retinol-binding protein 4, LV mass, and type 2 diabetes but inversely associated with body mass index and use of renin-angiotensin system blockers." (PMID 40604004, 2025). "The augmentation of RBP4 has been demonstrated as a marker of type 2 diabetes, the severity of atherosclerosis, and the risk of cardiovascular events in population studies." (PMID 38256272, 2024). "RBP4, known to be an adipokine associated with hyperinsulinemia and type II diabetes in obese individuals, has previously been identified as a serum marker for multiple cancers, including breast, colorectal and ovarian cancers." (PMID 38913193, 2024). "The serum level of RBP-4 was found to be associated with proliferative diabetic retinopathy and coronary cerebrovascular or peripheral vascular diseases among type 2 diabetes." (PMID 36271990, 2023). "Previously, a U-shaped association was described between circulating RBP4 and the risk of incident of type 2 diabetes in middle-aged Chinese prediabetic patients and in women with high cardiometabolic risk." (PMID 36837889, 2023). "Retinol and retinol-binding protein 4 (RBP4) were associated with type 1 diabetes and type 2 diabetes." (PMID 35745841, 2022). "A recent nested case-control study performed in Singapore Chinese has reported a sex-specific association of RBP4 with risk of type 2 diabetes." (PMID 35634496, 2022). "Recent research reported a U-shaped relationship between serum RBP4 levels and the risk of incident type 2 diabetes in subjects with prediabetes." (PMID 35634496, 2022). "In contrast, an inverse association between RBP4 levels and cardiovascular mortality [HR (95% CI) for cardiovascular mortality, tertile 3 versus tertile 1: 0.73 (0.50, 1.07)] was observed among 950 type 2 diabetes patients with 22 years of follow-up." (PMID 34419052, 2021). "In people with NGT or prediabetes at baseline, the highest tertile of RBP4 was associated with a 5.48-fold and 2.43-fold higher risk of progression to type 2 diabetes, respectively." (PMID 31690939, 2020). "Previous studies have suggested that serum RBP4 concentrations were associated with insulin resistance, metabolic syndrome, impaired glucose tolerance, and type 2 diabetes." (PMID 32774120, 2020). "Nevertheless, the prospective study that was excluded from the current meta-analysis has reported a significant association between RBP4 and type 2 diabetes risk among 147 Asian Indian men with prediabetes (OR per SD: 1.65; 95% CI 1.03–2.66)." (PMID 30651745, 2019). "We then examined if the association between RBP4 and type 2 diabetes risk was different among participants with different characteristics in men and women separately." (PMID 30651745, 2019). "The coding region of RBP4 is located at chromosome 10q23–24 in humans, contains 5 exons and 6 introns, and has been linked to increased risk for type 2 diabetes in various populations." (PMID 26975349, 2016). "Still, prospective studies have reported longitudinal associations of RBP4 with the incidence of type 2 diabetes and cardiovascular disease (CVD) in humans." (PMID 26402656, 2015). "If FPG was replaced by 2hPG in both models, lipocalin-2 or RBP4 remained as a significant factor associated with subclinical atherosclerosis in type 2 diabetes (OR 2.28, 95% CI 1.08–4.83, P = 0.031; OR 1.15, 95% CI 1.09–1.21, P<0.001, respectively)." (PMID 23799122, 2013). "The A allele of RBP4 −803GA polymorphism was linked to an increased risk of type 2 diabetes in non HIV-infected population." (PMID 23145084, 2012). "Null associations with RBP4 as we report here in healthy midlife women have also been reported in type 2 diabetes patients, both for CIMT and for other measures of peripheral subclinical disease including ankle-brachial index and carotid/femoral echography." (PMID 22587616, 2012).
type 2 diabetes (continued). "Identification of STRA6 as a cell surface receptor for RBP4 provides further link in this axis and hence we analyzed SNPs in these three genes for association with type 2 diabetes in a South Indian population." (PMID 20625434, 2010). "SNPs in STRA6, gene coding the cell surface receptor for RBP4, were significantly associated with type 2 diabetes and further genetic and functional studies are required to understand and ascertain its role in the manifestation of type 2 diabetes." (PMID 20625434, 2010). "They identified a functional variant (rs3758539) in the promoter of RBP4 associated with type 2 diabetes." (PMID 20625434, 2010). "SNPs in RBP4 have been previously reported to be associated with type 2 diabetes in Mongolian population." (PMID 20625434, 2010). "Though association studies pertaining to SNPs in RBP4 with type 2 diabetes and related parameters have been done in many populations, detailed studies of SNPs in GLUT4 with type 2 diabetes is lacking." (PMID 20625434, 2010). "Accordingly, increased serum levels of RBP4 are found in obese and diabetic individuals, and polymorphisms in the rbp4 locus are associated with type II diabetes." (PMID 19390610, 2009). "Given the linear association, we also estimated the risk of type 2 diabetes associated with every 1-log μg/mL increment in RBP4 levels, and the OR (95% CI) in model 2 was 1.38 (0.71–2.65) in the whole study population, 0.63 (0.21–1.84) in men and 2.78 (1.09–7.14) in women." (PMID 30651745, 2019). "Although the underlying mechanisms for the observed sex-heterogeneity are not fully understood yet, estrogen may have a regulatory role in RBP4 levels and this may explain the interaction between RBP4 levels and sex in influencing type 2 diabetes risk." (PMID 30651745, 2019). "However, since no other study has examined the impact of impaired glucose tolerance on the association between RBP4 and type 2 diabetes risk in men with prediabetes, further studies are warranted." (PMID 30651745, 2019). "Therefore, more studies with sufficient sample size in men and women separately are needed to examine the feasibility of targeting RBP4 through these pharmacological and lifestyle interventions to reduce the risk of type 2 diabetes in high-risk populations." (PMID 30651745, 2019). "Furthermore, high RBP4 levels have been observed in obese subjects, type 2 diabetic patients, adolescents with cardiovascular risk factors, and nonobese individuals low insulin sensitivity suggesting a pathogenic link between RBP4 and IR in humans." (PMID 29333450, 2017). "Further, manipulations of GLUT4 expression and RBP4 levels in mice suggest that RBP4 may play a causal role in the pathogenesis of type 2 diabetes." (PMID 23936766, 2013). "Similarly, if lipocalin-2 was replaced by RBP4 in the model, RBP4 was independently associated with subclinical atherosclerosis in type 2 diabetes (OR 1.16, 95% CI 1.10–1.22, P<0.001)." (PMID 23799122, 2013). "We finally uncover a conserved molecular mechanism for this process involving the production of the secreted lipocalin Neural Lazarillo (NLaz), an ortholog of the vertebrate Retinol Binding Protein 4 (RBP4) implicated in the onset of type II diabetes (T2D) in mice and human." (PMID 22567167, 2012). "Furthermore, common haplotypes in GLUT4 and RBP4 were also found to be associated with type 2 diabetes." (PMID 20625434, 2010). "Therefore, it remains unclear whether RBP4 will be a useful risk marker for type 2 diabetes in both men and women." (PMID 30651745, 2019). "Therefore, to examine sex-specific association between plasma RBP4 levels and type 2 diabetes in a prospective manner, we first conducted a case-control study nested within the Singapore Chinese Health Study cohort, with comprehensive adjustment for potential confounders and subgroup analyses." (PMID 30651745, 2019).
type 2 diabetes (continued). "Since we did not have information on estrogen level, whether estrogen plays an important role in the association between RBP4 and type 2 diabetes risk remains to be explored, and more mechanistic studies are needed to elucidate the reason for the difference in results between men and women." (PMID 30651745, 2019). "Therefore, we speculated that plasma RBP4 might be associated with DR in Chinese patients with type 2 diabetes." (PMID 30135138, 2018). "Furthermore, RBP4 levels were also elevated in patients with chronic kidney diseases, raising the question to which extent the direct association of RBP4 levels with prevalent type 2 diabetes might be explainable by early renal complications." (PMID 26402656, 2015). "Furthermore, RBP4 −803GA polymorphism (rs3758539), located at 5′ upstream of the translational start site within a putative enhancer region, is associated with an increased risk of type 2 diabetes in non HIV-infected patients." (PMID 23145084, 2012). "RBP4 is also associated with reduced clearance of VLDL-apoB100, positively correlating with triglycerides and large VLDL levels in patients with type 2 diabetes." (PMID 41303567, 2025). "Elevated RBP4 concentrations have also been associated with microalbuminuria, CKD, and clinical atherosclerosis in individuals with type 2 diabetes." (PMID 40881125, 2025). "Elevated serum levels of RBP4 have been observed in individuals with insulin resistance and type 2 diabetes." (PMID 38791060, 2024). "A subsequent study showed that in obese and type 2 diabetic patients, circulating RBP4 level was positively related to metabolic syndrome and IR." (PMID 36670387, 2023). "It was found that alterations in RBP4 in patients with type 2 diabetes were also attributed to the changes of renal function." (PMID 35309061, 2022). "were the first to report elevated serum RBP4 levels with increasing serum uric acid among 885 individuals with type 2 diabetes in Taiwan." (PMID 35846279, 2022). "IL-6, leptin, and RBP4 levels were higher in those who developed type 2 diabetes than in the other groups." (PMID 31690939, 2020). "RBP4 level was significantly higher in the prediabetes-to–type 2 diabetes group than in those who were remained in the prediabetes group." (PMID 31690939, 2020). "Those with prediabetes in the highest tertile of RBP4 was 2.43-times more likely to convert to type 2 diabetes than were those in the lowest tertile (95% CI, 1.10–5.34; P = 0.028)." (PMID 31690939, 2020). "Retinol binding protein 4 (RBP4) was first identified as an adipocyte-derived factor that contributes to the pathogenesis of type 2 diabetes." (PMID 32095874, 2020). "In conclusion, during the 10-year observation period, higher levels of serum RBP4, resistin, and PAI-1 were associated with the risk of developing prediabetes or type 2 diabetes and lower serum adiponectin level was a predictor of future prediabetes." (PMID 31690939, 2020). "In this 10-year prospective study, NGT with higher serum RBP4 and PAI-1, and with lower adiponectin were associated with new-onset prediabetes and type 2 diabetes." (PMID 31690939, 2020). "Participants in the NGT group in the highest RBP4 tertile were 5.48-times more likely to develop type 2 diabetes than were those in the lowest tertile (95% CI, 1.87–16.03; P = 0.002)." (PMID 31690939, 2020). "Plasma RBP4 levels were measured among 571 incident type 2 diabetes cases and 571 controls nested within the Singapore Chinese Health Study." (PMID 30651745, 2019). "Abnormal mitochondrial oxidative phosphorylation occurs in obese girls with type 2 diabetes and IR, which are related to RBP4." (PMID 31412686, 2019). "Retinol binding protein (RBP4) is an adipokine that may be linked to type 2 diabetes (T2DM), which leads to cardiovascular disease (CVD)." (PMID 29747616, 2018).
type 2 diabetes (continued). "Hypertriglyceridemia (p < 0.001 for both sexes), occurrence of type 2 diabetes or fasting plasma glucose over 100 mg/dL (p < 0.01, p < 0.05 for women and men, respectively) were substantially related to RBP4 levels." (PMID 29524177, 2018). "The present study shows that elevated plasma levels of RBP4 were associated with DR and VDTR in Chinese patients with type 2 diabetes, suggesting a possible role of RBP4 in the pathogenesis of DR complications." (PMID 30135138, 2018). "Cumulative evidences showed that overexpression of RBP4 from adipose tissues promote hyperinsulinemia and type II diabetes." (PMID 29642915, 2018). "The aim of the present study was to investigate the relationship between plasma RBP4 levels and DR, and to determine its possible role in type 2 diabetes." (PMID 30135138, 2018). "Higher plasma RBP4 levels were reported in insulin-resistant humans and mice as well as patients with type 2 diabetes, hypertriglyceridemia, atherogenic dyslipidaemia, and hypertension." (PMID 29524177, 2018). "The objective of this study was to elucidate the relationship between RBP4, TTR, triglyceride (TG) and type 2 diabetes risk in rural Thailand." (PMID 29747616, 2018). "Exercise training also reduced circulating RBP4 levels and resistance training decreased circulating RBP4 in people with type 2 diabetes." (PMID 30374329, 2018). "A relatively large study of patients with type 2 diabetes or CAD previously reported the relation of RBP4 levels to an unfavorable lipid profile." (PMID 25142320, 2014). "In conclusion, our study suggests that serum lipocalin-2 or RBP4 levels reflect subclinical atherosclerosis in adults with newly diagnosed type 2 diabetes." (PMID 23799122, 2013). "Some studies demonstrated that glucose transporter-4 (GLUT4) protein expression in muscle cells was inversely correlated with plasma RBP-4 concentrations in obese subjects with impaired glucose tolerance or type 2 diabetes." (PMID 24367155, 2013). "Serum levels of retinol-binding protein-4 (RBP4) correlate inversely with insulin sensitivity in patients with type 2 diabetes." (PMID 23781325, 2013). "Taken together, it is possible that lipocalin-2 and RBP4 mediate atherogenesis via enhancing vascular inflammation in type 2 diabetes." (PMID 23799122, 2013). "In this study, we assessed serum lipocalin-2 and RBP4 concentrations in patients with newly diagnosed type 2 diabetes in relation to subclinical atherosclerosis, as measured by carotid, femoral and iliac arteries." (PMID 23799122, 2013). "Retinol-binding protein-4 (RBP4) is a protein and its serum levels are increased in patients with type 2 diabetes and correlate positively with several components of the metabolic syndrome." (PMID 23781325, 2013). "RBP4 correlates with serum TG levels in type 2 diabetic patients independent from liver fat content." (PMID 23671852, 2013). "For instance- Retinol Binding Protein-4 has been reported to be a biomarker for renal dysfunction and cardiovascular disease in type 2 diabetes." (PMID 21931718, 2011). "The inverse relationship between GLUT4 and RBP4 expression is known to play a role in the pathogenesis of type 2 diabetes." (PMID 20625434, 2010). "In conclusion, we analyzed SNPs in three candidate genes namely, GLUT4, RBP4 and STRA6 for association with type 2 diabetes." (PMID 20625434, 2010). "We also analyzed SNPs in RBP4 and GLUT4 for association with type 2 diabetes and related parameters." (PMID 20625434, 2010). "In this study, SNPs in GLUT4, RBP4 and STRA6 were analyzed for association with type 2 diabetes in a South Indian population." (PMID 20625434, 2010). "Our gene-gene interaction data reveals that when the sentinel SNPs in STRA6, RBP4 and GLUT4 are combined together they increase the prevalence of type 2 diabetes with increase in the number of risk alleles." (PMID 20625434, 2010).
type 2 diabetes (continued). "In women, elevated RBP4 levels were associated with a higher risk of type 2 diabetes, whereas no such relationship was observed in men." (PMID 40871724, 2025). "In 1997, it was reported that RBP4 was elevated in the blood of type 2 diabetes patients." (PMID 39698033, 2024). "The inhibitory effect of Cy-3-glucoside on retinol-binding protein 4 (RBP4) expression and the enhancing effect on glucose transporter 4 (Glut4) in the adipose tissue were highlighted in KK-A(y) type 2 diabetes mice after a diet with 0.2% anthocyanin for 5 weeks." (PMID 35807504, 2022). "In the nested case-cohort study from Singapore Chinese, higher risk of type 2 diabetes corresponding to increased plasma RBP4 levels was only observed in women but not in men, the results were still consistent after pooled with two prior studies." (PMID 35634496, 2022). "Participants with the highest tertile of resistin and RBP4 were 2.34- and 2.64-times more likely to develop type 2 diabetes compared with those in the lowest tertile (95% confidence interval [CI], 1.43–3.81; P = 0.001; and 95% CI, 1.59–4.37; P < 0.001, respectively)." (PMID 31690939, 2020). "Mechanistic studies have shown that RBP4 may be involved in several etiologic pathways leading to type 2 diabetes development, such as dysregulation of insulin resistance and insulin secretion, inflammation, and failure of intracellular lipid homeostasis." (PMID 30651745, 2019). "Increased plasma RBP4 levels were associated with higher risk of type 2 diabetes in women but not in men." (PMID 30651745, 2019). "This suggests that the association between RBP4 and type 2 diabetes was independent of those pathways in women." (PMID 30651745, 2019). "Only a small study including 92 patients with type 2 diabetes described that RBP4 may be a novel biomarker for its diagnosis and treatment in diabetic patients." (PMID 30135138, 2018). "Plasma RBP4 concentrations were tested in 287 patients with type 2 diabetes." (PMID 30135138, 2018). "It has been shown that RBP4 serum levels are associated with kidney function rather than type II diabetes in nondialytic population with moderate kidney disease." (PMID 29333450, 2017). "The retinol binding protein-4 (RBP4) gene is located in this region and various studies showed that single nucleotide polymorphisms (SNPs) rs3758539, rs34571439, and rs116736522 in the RBP4 gene increased the risk of type 2 diabetes." (PMID 24665145, 2014). "Serum levels of lipocalin-2 and RBP4 were measured in 284 type 2 diabetic patients." (PMID 23799122, 2013). "RBP4 levels were significantly higher in patients with metabolic syndrome and type 2 diabetes than in euglycemic subjects (42.9±14.6; 42.3±17.0 and 37.4±11.7 μg/ml, respectively) and correlated with triglycerides but not with those of HOMA-IR in the whole population." (PMID 24223837, 2013). "Furthermore, recent studies have shown that RBP4 mainly correlates with dyslipidemic profiles in type 2 diabetes, especially in terms of hypertriglyceridemia." (PMID 23671852, 2013). "Association analysis of selected SNPs in STRA6, RBP4 and GLUT4 with type 2 diabetes." (PMID 20625434, 2010). "Additionally several studies in various populations have reported elevated levels of RBP4 in type 2 diabetes and related metabolic parameters." (PMID 20625434, 2010). "Another study which analyzed SNPs in the RBP4 for association with type 2 diabetes identified a common haplotype associated with type 2 diabetes but failed to observe any single SNP association." (PMID 20625434, 2010). "Additionally haplotype analysis with SNPs in RBP4 and GLUT4 also revealed significant association of a common haplotype in both genes with type 2 diabetes." (PMID 20625434, 2010). "Retinol binding protein 4 may contribute to the pathogenesis of nonalcoholic fatty liver disease in type 2 diabetics." (PMID 19919702, 2009).